KIAA1210 (KIAA1210)
Tractability: No criterion of Open Targets' tractability assessment is met for any kind of drug.
Gene: Protein-coding gene on chromosome X (119,078,635 to 119,150,579, reverse strand). Ensembl gene ENSG00000250423.
Subcellular location: Cytoplasmic vesicle, secretory vesicle, acrosome
Subcellular location (Human Protein Atlas): Golgi apparatus; Vesicles
Gene Ontology:
Cellular component: acrosomal vesicle; basal ectoplasmic specialization
Homologues: Orthologues: chimpanzee KIAA1210 (99% identical), macaque KIAA1210 (92% identical), dog KIAA1210 (50% identical), rat Kiaa1210 (38% identical), mouse Gm14569 (31% identical), zebrafish cracdla (9% identical), zebrafish cracdlb (7% identical), Drosophila melanogaster Cow (2% identical), Caenorhabditis elegans test-1 (1% identical). Paralogues in human: SPOCK2 (3% identical), SPOCK3 (3% identical), SPOCK1 (2% identical).
Diseases named in the same sentence as KIAA1210 in open-access papers:
KIAA1210 is named in the same sentence as 2 diseases in open-access papers, as found by Europe PMC text mining. Sharing a sentence is not in itself a finding about the gene and the disease. The quoted sentences say what the papers report.
osteoarthritis (1 paper, 2022). A noninflammatory degenerative joint disease occurring chiefly in older persons, characterized by degeneration of the articular cartilage, hypertrophy of bone at the margins and changes in the synovial membrane. "Alteration in KIAA1210 is found to be associated with maintaining homeostasis in joints affected by osteoarthritis." (PMID 36105105, 2022).
KIAA1210 also shares sentences with these, for which no sentence is quoted: Infertility (1 paper).